MIR3180-1 (microRNA 3180-1)
Synonyms: hsa-mir-3180-1
Gene: MicroRNA gene on chromosome 16 (14,911,220 to 14,911,313, forward strand). Ensembl gene ENSG00000265537.
Gene Ontology:
Biological process: miRNA-mediated post-transcriptional gene silencing
Homologues: Paralogues in human: MIR3180-3 (100% identical).